CEACAM1 (CEA cell adhesion molecule 1)
Diseases named in the same sentence as CEACAM1 in open-access papers (continued):
Sharing a sentence is not in itself a finding about the gene and the disease.
tumor (continued). "The heterophilic interaction between CEACAM5 on tumour cells and CEACAM1 on NK cells has been demonstrated to inhibit NK cell-mediated anti-cancer immunity." (PMID 36494785, 2022). "Relevant to this aspect, CEACAM-1 has been recognized as playing a dual role in colorectal cancerogenesis, possibly tumor-suppressive in the early phases, and supportive for malignant progression and metastasis in advanced disease." (PMID 36139097, 2022). "There has been evidence about CEACAM1‐mediated apoptosis in exacerbates hypoxic cardiomyocyte injury and post‐infarction cardiac remodeling, and early tumor development." (PMID 35657334, 2022). "NEO-201 can block the interaction between CEACAM-5 expressed on tumor cells and CEACAM-1 expressed on NK cells to reverse CEACAM-1-dependent inhibition of NK cytotoxicity." (PMID 35804808, 2022). "Several studies have shown that binding between CEACAM-1 on NK cells and CEACAM-1 or CEACAM-5 on tumor cells inhibits NK activation signaling mediated by NKG2D." (PMID 35804808, 2022). "We found that Fn stably adheres to CSCs, likely by multiple interactions involving the tumor-associated Gal-GalNac disaccharide and the Fn-docking protein CEA-family cell adhesion molecule 1 (CEACAM-1), robustly expressed on CSCs." (PMID 36139097, 2022). "Galectin 9 is expressed in multiple cell types, with CEACAM1 also being highly expressed by some tumor cells." (PMID 34638305, 2021). "In view of this, the evaluation of their ligand expression, such as CEACAM-1 for Tim-3 and LSECtin for Lag-3, on tumor cells is important to prove the inhibition by their axis in the tumor microenvironment." (PMID 33611641, 2021). "Due to its multifaceted role as a recently appreciated immune checkpoint inhibitor and tumor marker, CEACAM1 is an attractive target for cancer immunotherapy." (PMID 34908921, 2021). "CEACAM1 appears to play an important role in tumor growth and progression by participating in immune evasion mechanisms, as well as an angiogenic effect." (PMID 34943606, 2021). "We previously demonstrated that F. nucleatum binds and activates the human inhibitory receptors TIGIT and CEACAM1 leading to inhibition of T and NK cell anti-tumor immunity." (PMID 34395310, 2021). "Patients with low CEACAM1 expression on tumor cells and low CEACAM1+ TILs infiltration had a more favorable outcome." (PMID 34368221, 2021). "HLA class II (ligand for LAG3), PD-L1 (ligand for PD-1), HLA-E (ligand for NKG2A), and CEACAM1 (ligand for TIM3) were all expressed on tumor organoids, suggesting that the opT cells were likely to be regulated by these checkpoint proteins." (PMID 34789550, 2021). "It has been shown that CEACAM1 is the main effector of vascular endothelial growth factor (VEGF) in the formation of tumor microvessels at an early stage." (PMID 34943606, 2021). "Selection often guides tumors to overexpress CEACAM1 in order to bind and activate CEACAM1 on immune cells and escape anti-tumor activity." (PMID 34395310, 2021). "CEACAM1 mediates cell adhesion via homophilic binding (CEACAM1-CEACAM1) or heterophilic binding to carcinoembryonic antigen (CEA), a tumor-associated adhesion molecule." (PMID 34336716, 2021). "Depending on tumor type and histologic grading, CEACAM1 have apparently opposite actions, including tumor-suppressive or tumor-promoting function." (PMID 34368221, 2021). "Tumor infiltrating lymphocytes (TILs) found in the colorectal cancer microenvironment are characterized by high levels of CEACAM1, along with reduced levels of cytotoxic activity when compared to paraneoplastic T cells." (PMID 34395310, 2021). "In this regard, the novel T3/28 chimera, possibly targeting PtdSer, Gal-9, and CEACAM1 on the tumor cells, was developed to synergistically enhance the ability of engineered T cells to kill B lymphoma." (PMID 34853180, 2021). "Here we reported scores and absolute counts of TIM-3+/CEACAM1+ TILs, and evaluated the expression of CEACAM1 on tumor tissues." (PMID 34368221, 2021).
tumor (continued). "Due to its inhibitory functions in immune cells including T and NK cells, in addition to being expressed on tumor cells, CEACAM1 makes a promising target for immunotherapy." (PMID 33075095, 2020). "TIM-3 interacts with numerous ligands including tumour-secreted galectin-9, high-mobility group protein B1 (HMGB1), carcinoembryonic antigen cell adhesion molecule 1 (CEACAM-1, expressed on tumour cells), and phosphatidyl serine (PtdSer)." (PMID 32645977, 2020). "In the current study plasma levels of CEACAM1 were lower in patients with cancer compared to benign tumors, supporting the role of CEACAM1 as a tumor suppressor." (PMID 33075095, 2020). "In summary, biomarkers associated with both oncogenic (ITGAV, CEACAM1, CXCL1, IL-10RB) and tumor-suppressive actions (CEACAM1) were found to increase the diagnostic performance of HE4, CA125 and age in our study." (PMID 33075095, 2020). "The experiments investigating CEACAM1 in tumorigenesis denoted a pivotal role for CEACAM1 as a tumor suppressor." (PMID 31358815, 2019). "In the subcutaneous tumor model with NOD SCID mice, CEACAM1-4L transfected NUGC3 cells was more suppressed tumor growth than those with CEACAM1-4S or vector control." (PMID 31481751, 2019). "On the tumor cell surface, CEACAM1 has been shown to interact directly with CEACAM1 on NK cells and tumor-infiltrating lymphocytes (TIL), leading to functional inhibition of those cells." (PMID 30871206, 2019). "The central meaning of the homophilic CEACAM1 interaction in trans was also supported by reports showing that CEACAM1 positive NK cells inhibited cytolysis of CEACAM1 expressing tumor cells by impairing NKG2Ds ability to stimulate cytolysis." (PMID 30871206, 2019). "As a cell–cell communication molecule, CEACAM1 mediates the direct interaction between tumor and immune cells." (PMID 30871206, 2019). "CEACAM1 is a major effector of vascular endothelial growth factor (VEGF) in early tumor microvessel formation." (PMID 31039510, 2019). "Higher expression of CEACAM1 gene was associated with prolonged survival in KIRC and BLCA cancer patients after adjusting for the abundances of tumor infiltrating immune cells." (PMID 31358815, 2019). "CEACAM1-4L overexpression induced less invasion, more lumen formation, and less tumor growth of NUGC3 cells." (PMID 31481751, 2019). "On the other hand, CEACAM1-4S induced suppression of invasion, more lumen formation, and more tumor growth." (PMID 31481751, 2019). "CEACAM1 was involved in the processes of inflammation or tumor genesis, during which levels of CEACAM1 isoforms, or CEACAM1-S/CEACAM1-L changed in the pathological conditions." (PMID 31072323, 2019). "While on activated T cells, CEACAM1 and Tim-3 are co-expressed and form a heterodimer to suppress T cell function and downregulate its anti-tumor immunity." (PMID 30309387, 2018). "At the same time, CEACAM1 expression on the tumor cells has been shown to regulate NKG2D-ligand expression." (PMID 29973929, 2018). "CEACAM1 expression was observed at high levels on neutrophils, NK cells and myeloid-derived suppressor cells (MDSCs), while the expression on tumor-infiltrating CD8+ T cells was low." (PMID 30349641, 2018). "Taken together, the present study demonstrates low expression of CEACAM1 on tumor infiltrating mouse T cells, while significant expression was observed on B cells, NK cells and MDSCs." (PMID 30349641, 2018). "The emerging picture of CEACAM1 is extremely complex as its role in tumor cells appears to be contradictory, supporting both down- and upregulation." (PMID 30406153, 2018). "In mice, a significant fraction of tumor infiltrating CD8+ T cells have also been reported to express CEACAM1." (PMID 30349641, 2018). "The reason for apparent differences in tumor CEACAM1 expression profiles between our study and others is unclear." (PMID 30349641, 2018).
tumor (continued). "Due to its capacity to evade the immune system, as well as its potent proangiogenic effects, CEACAM1 appears to play an important role in tumor growth and progression." (PMID 30406153, 2018). "In order to validate that CEACAM1 protein is expressed in tumor cells, we performed immunohistochemistry with formalin-fixed, paraffin-embedded tumor samples (n = 15) from the Western blot cohort." (PMID 30050594, 2018). "Low or minimal expression of CEACAM1 on tumor infiltrating T cells suggests that the primary function of CEACAM1 in vivo is mediated via cells other than CD8+ T cells, and the potential role of CEACAM1 in immuno-oncology remains to be established." (PMID 30349641, 2018). "On the other hand, other investigations have suggested a role for CEACAM1 in angiogenesis and suppression of the neoantigen-specific anti-tumor response." (PMID 30349641, 2018). "CEACAM1 was shown to be a major effector of vascular endothelial growth factor (VEGF) in early tumor microvessel formation." (PMID 30406153, 2018). "Further, CEACAM1 localization in tumour tissue was evaluated by immunohistochemistry and CEACAM1 splice variants by RT-PCR in representative tumours." (PMID 30050594, 2018). "For example, CT26 tumor has relatively higher frequency of CEACAM1+CD4 T cells compared to MBT2 or MC38." (PMID 30349641, 2018). "We sought to investigate CEACAM1 expression on mouse tumor and immune cells, characterize CC1 mAb binding, and evaluate CC1 in syngeneic mouse oncology models as a monotherapy and in combination with an anti-PD-1 mAb." (PMID 30349641, 2018). "Metastatic load (adjusted for survival time and tumor weight) in the Luc control group was 14.7 times higher (95%-CI [2.4;91.3]; p = 0.006) in comparison with the CEACAM1 kd group." (PMID 30089785, 2018). "We found that CEACAM1 was expressed at relatively high levels on freshly harvested tumor infiltrating B, NK cells, and MDSCs, although the proportion of these cells was low." (PMID 30349641, 2018). "In multivariate Cox regression analysis including clinical stage, residual tumor after surgery, and nodal involvement, CEACAM1 remained a prognostic indicator for overall survival but lost its significance for recurrence-free survival." (PMID 30050594, 2018). "They analyzed the immunohistochemical expression of CEACAM1 in tumor samples from 145 patients with completely resected NSCLC." (PMID 30406153, 2018). "Ligation of CEACAM1-L isoforms on NK cells by CEACAM1 on tumor cells suppresses NK cytolytic function as CEACAM1 on the NK cells negatively regulates NKG2D signaling." (PMID 29973929, 2018). "The proposed mechanism of CEACAM1 overexpression attracting more neutrophils to tumor sites is through IL-8 and CXCL-6 upregulation." (PMID 30406153, 2018). "This is in contrast with another study, which showed IDO to be mainly located in neoangiogenic (CEACAM1-positive) micro-vessels and to correlate with lower rates of tumor cell proliferation." (PMID 30050535, 2018). "Early experiments investigating CEACAM1 in tumorigenesis denoted a pivotal role for CEACAM1 as a tumor suppressor." (PMID 30349641, 2018). "In the gene expression microarrays, IGFBP7 – a potent tumor (and probably metastasis) suppressor in melanoma – was the gene with the highest upregulation in expression in the CEACAM1 knockdown tumors." (PMID 30089785, 2018). "Carcinoembryonic antigen-related cell adhesion molecule 1 (CEACAM1) has been reported to mediate both tumorigenic and anti-tumor effects in vivo." (PMID 30349641, 2018). "In order to further investigation on its role in OvCa, we analyzed CEACAM1 mRNA levels extracted from TCGA microarray data (n = 517) as well as CEACAM1 protein expression by Western blot analysis in a cohort of 242 tumor samples." (PMID 30050594, 2018). "CEACAM1-reduced expression has been reported in more than 85% of early colorectal adenomas and carcinomas leading to a supposed tumor growth inhibitor function of this adhesion molecule in CRC development." (PMID 30406153, 2018).
tumor (continued). "CEACAM1 association with short survival was reflected in our xenograft model of primary tumor growth and spontaneous metastasis in which both were significantly reduced by CEACAM1 knockdown increasing the animals’ survival." (PMID 30089785, 2018). "Tumors implanted in CEACAM1 deficient mice exhibited impaired growth rate and mouse anti-CEACAM1 Ab CC1 prevented tumor growth in combination with anti-PD-L1 or anti-TIM-3 mAbs." (PMID 30349641, 2018). "Our data on the prognostic impact of CEACAM1 expression support the theory that these two modes of OvCa progression represent different tumor types which rely on different biologic backgrounds." (PMID 30050594, 2018). "In metastatic cutaneous melanoma, 89% of lesions express CEACAM1, and CEACAM1 expression increases during tumor progression, while soluble CEACAM1 levels significantly correlate with the level of LDH." (PMID 30406153, 2018). "Co-blockade of TIM-3 and its ligand CEACAM1 also leads to enhanced anti-tumor immunity and improved elimination of tumors in mouse colorectal cancer models." (PMID 30309387, 2018). "Specifically, silencing of CEACAM1 in mouse and human tumor cells upregulates expression of NKG2D-ligands on the cell surface of the tumor cell and makes them more highly susceptible to NK cell-mediated cytotoxicity." (PMID 29973929, 2018). "CEACAM1-SFK interactions contribute to cell adhesion properties of eosinophils as well as tumor cells." (PMID 30406153, 2018). "Homo- or heterophilic CEACAM1 interactions have been shown to inhibit NK-killing, and are thought to contribute to tumor cell immune evasion." (PMID 30341336, 2018). "Previous studies have provided functional evidence for tumor growth modulating activities of CEACAM1." (PMID 30349641, 2018). "There has been an increasing interest by the oncology community to explore CEACAM1 as a potential target for cancer immunotherapy given its expression on tumor and immune cells and its potential immunomodulatory properties." (PMID 30349641, 2018). "CEACAM1 has been studied extensively in the immune system and cancer, where it was shown to be expressed on T cells, NK cells, and a variety of tumor cells." (PMID 29211042, 2017). "In univariate analyses, CEACAM1, CEACAM5 and CEACAM6 expression showed significant association with primary tumor site, while EPHA2 expression was associated with both lymphatic and venous invasion." (PMID 29262644, 2017). "Carcino embryonic antigen cell adhesion molecule 1 (CEACAM1), a member of the CEA gene family, is a cell adhesion molecule known to be associated with CRC tumor development and metastasis." (PMID 29262644, 2017). "In mice, TIM-3 and CEACAM1 monoclonal antibody treatment resulted in a reduced tumor burden when administered independently, and demonstrated an additive benefit when administered together." (PMID 29211042, 2017). "CEACAM1 also downregulates NKG2D ligand on the surface of tumor cells which potentially allows them to escape from the antitumor immunity induced by NKG2D‐expressing NK cells." (PMID 28332308, 2017). "Carcinoembryonic antigen‐related cell adhesion molecule 1 (CEACAM1) is expressed in a number of tumor cell types." (PMID 28332308, 2017). "-Inhibit cell proliferation.-Arrest cell cycle at G2/M phase-Upregulate tumor suppressor CEACAM1 gene expresion." (PMID 26840292, 2016). "Overexpression of CEACAM1 is widely reported, but some studies report that decreased expression occurs in some tumor types and at different tumor stages." (PMID 27074014, 2016). "CEACAM1 is important to tumor development and altered CEACAM1 expression has been reported in many cancers." (PMID 27074014, 2016). "Further, we measured trans-membrane CEACAM1 expression in tumor tissues using real-time PCR (RT-PCR) and Western blotting." (PMID 27074014, 2016). "Serum CEACAM1 level was higher in OS patients with low tumor grades (P < 0.05) and OS patients with distant metastases (P < 0.05)." (PMID 27074014, 2016).
tumor (continued). "So, we assessed CEACAM1 expression in OS and noted that CEACAM1 mRNA and protein were significantly increased in OS tissue compared to tumor-adjacent tissue." (PMID 27074014, 2016). "RT-PCR analysis revealed that mRNA expression levels of CEACAM1 were significantly increased in OS tumor tissues compared to tumor-adjacent tissue." (PMID 27074014, 2016). "Collectively, these results show that serum CEACAM1 reflects tumor burden, disease progression, and survival." (PMID 26688824, 2015). "Collectively, our results show the prognostic value of serum CEACAM1 in monitoring tumor burden and disease progression." (PMID 26688824, 2015). "In contrast, human serum CEACAM1 strongly and directly correlated with tumor burden (Pearson's R = 0.863, P value < 0.0001) and was detectable even at minor tumor volume of 14 mm3, implying its high sensitivity." (PMID 26688824, 2015). "CEACAM1 has been controversially discussed as tumor suppressor but also as driver for invasion in different tumor entities." (PMID 26539411, 2015). "The potential of serum CEACAM1 to reflect or predict response to therapy of metastatic melanoma patients with adoptive cell transfer of tumor infiltrating lymphocytes was also tested." (PMID 26688824, 2015). "Immunohistochemistry results showed that CEACAM1 protein was mainly expressed on cytoplasm or membrane of tumor cells, which was consistent with previous research." (PMID 24587171, 2014). "The effects of CEACAM1 in neoplasms and inflammatory cells on cells themselves have been elaborated." (PMID 24587171, 2014). "Overexpression of CEACAM1 on tumor cells correlated with more neutrophils infiltration to some extent through upregulating mRNA expression of IL-8 and CXCL-6." (PMID 24587171, 2014). "We explored the possible effect of the overexpressed CEACAM1 in tumor cells to neutrophils infiltration." (PMID 24587171, 2014). "We also observed that beyond tumor cells, the inflammatory cells in stroma also expressed strong CEACAM1." (PMID 24587171, 2014). "CEACAM1 protein has multiple functions, such as regulating cell proliferation, angiogenesis, immunoreaction, tumor invasion and infection of microorganisms etc." (PMID 24587171, 2014). "In the current study, we explored the expression of CEACAM1 and the count of neutrophils in TSCC tissues, their relationship and the possible effects of CEACAM1 from tumor cells on neutrophils." (PMID 24587171, 2014). "CEA-expressing tumor cells are more likely to resist immunosurveillance by interacting with NK cell receptor CEACAM-1." (PMID 24699516, 2014). "ROC analysis showed that the AUC for CEACAM1 remarkably exceeded 0.5 at 0.96, which strongly suggests the promising future of CEACAM1 as a tumour monitor." (PMID 23885995, 2013). "We compared the serum level of CEACAM1 in NSCLC patients with healthy donors and analyzed the location and expression of CEACAM1 in primary tumour tissues by immunohistochemical staining." (PMID 23885995, 2013). "This increase was correlated with disease progression, providing evidence for the potential value of soluble CEACAM1 as a tumour marker." (PMID 23885995, 2013). "We further sought to validate the expression of two adhesion molecules at the protein level using flow cytometry: CEACAM1, a tumor marker and broad inhibitor of T-cell function and MCAM, a Th17 marker and regulator of cell recruitment into the brain." (PMID 24359430, 2013). "The protein expression and the location of CEACAM1 in tumours were observed by immunohistochemical staining." (PMID 23885995, 2013). "In these tissues, CEACAM1 acts as a cell adhesion molecule, an angiogenic factor, a tumor suppressor, and a signal regulatory protein." (PMID 23613893, 2013).